CCL5 (C-C motif chemokine ligand 5)
Diseases named in the same sentence as CCL5 in open-access papers (continued):
Sharing a sentence is not in itself a finding about the gene and the disease.
breast cancer (continued). "However, these fibroblasts from benign hyperplasia could respond to cm from BRCA1 defective breast cancer cells with high induction of CCL5." (PMID 30224826, 2018). "Thus, NZ, by reducing IL-6 s and completely abolishing CCL5 secretion by MSCs may counteract the consequences of MSCs/PCa and MSCs/breast cancer interactions." (PMID 28477013, 2017). "Recombinant human CCL5 alone could significantly increase breast cancer cell migration." (PMID 29299159, 2017). "Moreover, CCL5 also boosts metastasis in ovarian and breast cancer cells." (PMID 29170526, 2017). "Furthermore, CCL5 is a predictor of disease progression in stage II breast cancer patients." (PMID 27335323, 2016). "Moreover, CCL5 enhances the invasive capacity of these breast cancer cells." (PMID 27335323, 2016). "MSCs have been associated with tumor growth and metastatic potential of breast cancer cells via activating EMT in cancer cells, increasing tumor-initiating cell populations, increasing vascular endothelial factor (VEGF) signaling, and inducing the secretion of the chemokine CCL5." (PMID 25887413, 2015). "Importantly, when focusing on CCL5, as it is known to promote breast cancer metastasis, we found that CCL5 was significantly increased in the CM of isolated neutrophils from JDP2−/− mice when compared to wild-type mice, as assessed by ELISA using pooled samples from 6 mice per group." (PMID 26497998, 2015). "In addition to having a pivotal role in basal breast cancer growth and metastasis, the secreted factors implicated in our previous study (IL6, CSF2, CCL5, VEGFA, and VEGFC) may also serve critical roles in other subtypes of breast cancers." (PMID 26173622, 2015). "In breast cancer, including TNBC, LSD1 has been identified as a repressive element for C-C motif chemokine ligand 5 (CCL5), CXCL9 and CXCL10 secretion." (PMID 41154396, 2025). "As noted by Lechner, heightened expression of CCL5/RANTES and FGF-2 correlates with the occurrence of neurodegenerative diseases, rheumatoid arthritis, and breast cancer." (PMID 40076479, 2025). "Breast cancer and stromal cells in TME cells secrete chemokines CCL2, CCL5 (RANTES), CCL20, CCL22, and CXCL12 which, by binding to the corresponding receptors, induce Treg homing to tumor tissue." (PMID 40940764, 2025). "Knockdown of HSF1 in breast cancer cells led to decreased tumor size and increased CD8 + T cell infiltration, which was mediated by CCL5." (PMID 40287736, 2025). "Preclinical studies have highlighted the promising role of maraviroc in anti-tumor therapies through the CCL5/CCR5 pathway, including breast cancer, colon cancer, glioblastoma, and gastric cancer." (PMID 41152972, 2025). "Chemokine (C-C motif) ligand 5(CCL5) and CCR5 signaling regulates the expression of CSF1 in breast cancer cells, while CSF1 and CSF1 receptor (CSF1R) signaling regulates the expression of CCL5 in mesenchymal stem cells." (PMID 39192979, 2024). "CCL5 is a chemokine involved in the activation of CD8+ T cells, and its expression influences the immune infiltration of breast cancer cells, CCL5 is closely related to disease-free survival." (PMID 39493752, 2024). "While the dependency on IFN-ɣ for CXCL9/10 induction was previously known, our data show the cooperation between IFN-ɣ and TNF-α in promoting the secretion of CCL5 and CXCL9 from breast cancer cells." (PMID 38167224, 2024). "Biologically, the DDIR effect in GOA, similar to breast cancer, appears to be driven by the chemokines CXCL10 and CCL5, the pro-inflammatory functions of which include T-cell recruitment and expansion." (PMID 38744099, 2024). "Cytotoxic stress from infiltrating lymphocytes stimulates breast cancer cells to produce CCL5, which activates CCR5 signaling and mobilizes TAMs, and TAM-derived factors (OPN, HB-EGF, and IL-6) stimulate breast cancer cell growth." (PMID 39199574, 2024).
breast cancer (continued). "This concordance suggests a somewhat coordinated coexpression of the chemokines CCL2 and CCL5 in MIBC, as has been reported in breast cancer." (PMID 38928033, 2024). "The results showed that 5 genes, APOA5, CCDC28B, CCL5, SERPINA12, and WT1, were significantly overexpressed in breast cancer patients (P < 0.05)." (PMID 38676834, 2024). "Cancer cell-derived lactate increases the secretion of CCL5 through Notch signaling in TAMs, and CCL5 in turn induces EMT and aerobic glycolysis in breast cancer cells." (PMID 36670988, 2023). "CCL5 also enhanced survival, aerobic glycolysis, and epithelial-mesenchymal transition (EMT) of breast cancer cells." (PMID 36709284, 2023). "For instance, CXCL12, CCL2, CCL5, and CXCL1 have been shown to regulate growth and stimulate the proliferation of melanoma, glioma, prostate cancer cells, and breast cancer cells." (PMID 37762405, 2023). "Breast cancer cells induce the expression of cytokines (CCL2, CCL5, IL-1β, and IL-6) and immunomodulators (COX2, HIF-1α, VEGFα, and PD-L1) by cancer-associated adipocytes." (PMID 36670988, 2023). "Elevated levels of the chemokine CCL5 and its receptor CCR5 have been found in more than 58% of TNBC and HER-2+ subtype breast cancer clinical tumor samples." (PMID 37445941, 2023). "A study of 2245 human breast cancer samples showed increased expression of CCR5 and its ligand CCL5 in most basal and HER2 subtypes." (PMID 37759462, 2023). "High levels of CCL5 and CXCL10 in breast cancer correlate with advanced stages of the disease and reduced survival of metastatic breast cancer patients, respectively." (PMID 36949770, 2023). "More interestingly, aerobic exercise plays a protective role in primary cancer development and progression by regulating the levels of chemokines CCL2, CCL5, and their related receptors CCR2, and CCR5 in breast cancer." (PMID 36976529, 2023). "The CAAs modulate, for instance, the behavior of breast cancer cells via the release of pro-inflammatory mediators such as IL-6, TNF-α, CCL2, or CCL5, promoting angiogenesis, proliferation, and metastasis." (PMID 37686315, 2023). "As demonstrated in a mouse xenograft model of melanoma and breast cancer, MSCs secreted chemokines, namely CCL2, CCL5, CCL9, and CXCL10, which activated tumor cell migration and invasion, promoting the development of lung, bone, and lymph node metastases." (PMID 37686315, 2023). "Both findings were more pronounced in ER-positive patients, indicating the potential use of CCL5 and CCL19 as biomarkers or drug targets in future studies for breast cancer prevention and treatment." (PMID 36685922, 2022). "In the current study, we demonstrate that the lncSNHG5-ZNF281 signaling axis in breast CAFs plays a central role in lung PMN formation in breast cancer by regulating CCL2 and CCL5 expression." (PMID 36438499, 2022). "In basal-like and BRCA1-related breast cancers, ROS expression was correlated with AhR levels and the expression of the chemokines CXCL1, CXCL2, and CCL5." (PMID 36588678, 2022). "We observed that miR-155 dramatically upregulated CCL5 and CXCL9/10/11 expression in breast cancer cells." (PMID 35925680, 2022). "CCL5 affects the Treg/CD4+CCR5+ cell ratio in breast cancer patients through CCR5, thus affecting breast cancer metastasis and prognosis." (PMID 36033472, 2022). "For example, Met-CCL5, an antagonist of CCR5, reduced the frequency of infiltrating macrophages in a murine model of breast cancer." (PMID 33603130, 2022). "Even other molecules that increase CCL5 levels, such as IL-6 and HER2-PTEN, contribute to breast cancer development." (PMID 36430633, 2022). "With respect to the seven measured chemokines, CXCL5 and CCL23 were substantially decreased in the group of breast cancer patients, while those of CX3CL1 (fractalkine) and CCL5, were significantly elevated." (PMID 35677046, 2022).
breast cancer (continued). "PTP1B upregulates the expression of CCL5 in breast cancer cells; therefore, PTP1B inhibition can be a promising approach for the treatment of breast cancer." (PMID 35159385, 2022). "Comparison of tumors from NeuT/ATTAC+AP mice with biopsies of HER2+ breast cancer for fibrosis markers indicated several commonalities, including FAP (fibroblast activation protein), Ccl5, S100aA9 and collagen expression." (PMID 33780491, 2021). "RANTES, also known as CCL5, plays a central role in the interaction of MSC with the tumor stroma and thus supports the mechanisms of metastasis of breast cancer." (PMID 33946741, 2021). "Met-CCL5, a competitive CCR5 inhibitor, reduces breast cancer proliferation and infiltrating macrophages in animal preclinical models." (PMID 33747948, 2021). "In breast cancer, MSCs secrete VEGF, SDF-1, and CCL5, which enhance breast cancer cell mobility and invasiveness and induce EMT in primary tumor cells, which aids in metastasis to secondary locations." (PMID 34322780, 2021). "When adipocytes are co-cultured with breast cancer cells, cytokines are secreted, specifically IL-8, IL-6, IFNγ-inducible protein 10, CCL2, and CCL5." (PMID 34912237, 2021). "A more detailed analysis of 1100 patients with breast cancer (BRCA) revealed significant positive correlations between Il12b, Ifng, Ccl4, Ccl5, Cxcl9, and Cxcl10 gene expression levels and tumor infiltration of CD8+ T cells and M1 macrophages." (PMID 34446712, 2021). "Breast cancer cell lines MDA-MB-231 and MDA-MB-435 are known to secrete CCL5 to increase the development of MDSC and metastasis." (PMID 33780491, 2021). "Another chemokine, CCL-5, shows similar abilities as CCL-2 in breast cancer progression, for example, through the attraction of TAMs." (PMID 34944905, 2021). "This study demonstrates that oestrogen deprivation increases breast cancer secretion of TNF, CCL5, IL-6, IL-8, and CCL22 and alters total human peripheral blood mononuclear cell migration in an in vitro assay." (PMID 34602068, 2021). "Elevated CCL5 (RANTES), CCL2 (MCP-1), and CXCL8 (IL-8) in TNFα/IL-1β primed triple-negative subtype of breast cancer cells (TNBCs): hBMMSCs co-cultures increase BCC lung metastases." (PMID 33849537, 2021). "We therefore immunolocalized CCL5, as well as CCR1, 3 and 5, in 111 human breast carcinoma tissues and correlated them with clinicopathological characteristics." (PMID 33671956, 2021). "When we correlated immunoreactivity for CCL5, CCR1, 3 and 5 with the clinicopathological factors of 111 breast carcinoma tissues." (PMID 33671956, 2021). "For example, CCL2, CCL5, CXCL8, and CXCL12 can promote breast cancer, while CXCL9, CXCL10, and CCL16 can inhibit breast cancer." (PMID 32253815, 2020). "Under hypoxic conditions, breast cancer cells strongly increase CCR5 and CCL5 expression, thereby stimulating cancer cell migration." (PMID 32630699, 2020). "CCL5/RANTES expression is increased in acute myeloid leukemia cells, multiple myeloma cells, MDA-MB-231 and MDA-MB-435 breast cancer cells, cervical squamous carcinoma cells, and primary rat astrocytes." (PMID 32781743, 2020). "In vivo studies demonstrate the involvement of the CCL5/CCR5 axis in lung metastasis and colonization after the injection of breast cancer cells and MSCs in mice." (PMID 32630699, 2020). "The CCL5/CCR5 interaction appears to modulate directional tumor migration and metastasis in different types of cancers, such as lung and breast cancer, as well as osteosarcoma." (PMID 32847038, 2020). "The CCL5/CCR5 axis has been reported as a mechanism of tumor progression in pancreatic, gastric, and breast cancer." (PMID 32545571, 2020). "In patients with breast cancer, CCR5 and its ligand CCL5 were found to be upregulated among DEGs in the pCR group." (PMID 33138797, 2020).
breast cancer (continued). "In EO771 mammary carcinoma cells, knockdown of PLAC1 resulted in the reduced expression of several inflammatory and immune factors, including Cxcl1, Ccl5, Ly6a/Sca-1, Ly6c, and leukemia inhibitory factor." (PMID 32499871, 2020). "Chemokines such as CCL2, CCL5, CCL4, and CXCL8 are also involved in the incidence and development of breast cancer." (PMID 31398937, 2019). "It is important to note that while our studies focus on the function of CCL5 in recruiting CCR5+ macrophages, breast cancer cells themselves can also express CCR5." (PMID 30990165, 2019). "Inflammatory factors (CCL5, IL-6, etc.)and transporters (MCT1, CD36, etc.)are potential targets for breast cancer treatment." (PMID 31500658, 2019). "Velasco-Velázquez’s study found that the CCL5-CCR5 axis is highly activated in TNBC− and human epidermal growth factor receptor-2 (HER2)-positive breast cancers and that CCR5+ cells respond to CCL5." (PMID 31500658, 2019). "Lactic acid produced by breast cancer cells supports TAM M2 polarization and their production of CCL5 by increasing Notch1 and Jagged2 mRNA and protein expression." (PMID 30154786, 2018). "In the BM1 as well as 4T1 mammary tumor models, forced expression of Raf kinase inhibitory protein (RKIP) suppresses CCL5 secretion from cancer cells and reduces TAM accumulation in the xenograft." (PMID 30483271, 2018). "Chemokines with well-known functions in mammary cancer include CCL2, CCL5, CCL19, CCL20, CCL21 and CCL22." (PMID 30572845, 2018). "The role of ASCs in regulating breast cancer is confounding due to varied nature of secreted adipokines, such as CCL5, which enhances the motility of MCF-7 breast cancer cell in vitro." (PMID 30060511, 2018). "Both the CC chemokine ligand 5 (CCL5/RANTES) and interleukin-6 (IL-6), released by mesenchymal stem cells (MSCs) as well as by neoplastic cells, promote breast cancer cell progression through autocrine and paracrine mechanisms." (PMID 29707128, 2018). "Further, human breast cancer tissues can express high levels of CCL2 and CCL5 compared to the adjacent normal breast tissues." (PMID 30483271, 2018). "Increasing evidence indicates that CCL5 and CCR5 are overexpressed in breast cancer, and CCR5 antagonists block metastasis of breast cancer." (PMID 27894093, 2017). "CCL5 has a crucial role in the metastasis of breast cancer cells and expression of CCR5 on breast cancer cells enhances cellular invasion by 40-fold." (PMID 29216863, 2017). "IL-8 has been proven to mediate chemoresistance in breast cancer in our previous report, herein we aimed to investigate the possible role of CXCL1 and CCL5 in hAdSCs-induced doxorubicin resistance in TNBC." (PMID 28750689, 2017). "Despite the demonstration that CCL4 secretion was lower than that of CCL5, CCL4 was found to be produced by breast cancer cells." (PMID 29299159, 2017). "For instance, in a previous study with in vitro and in vivo models using MDA-MB-231 human breast cancer cells, it was demonstrated that tumor-derived osteopontin (OPN) induces mesenchymal stem cells (MSC) production of CCL5, mediating metastasis." (PMID 29197379, 2017). "Reciprocally, CCL5 increased cell migration, induced cancer cell EMT, and promoted aerobic glycolysis in breast cancer cells, suggesting a positive metabolic feedback loop in the co-culture system." (PMID 29299159, 2017). "We found high levels of RANTES/CCL5, MCP-1/CCL2, and G-CSF in the breast cancer individual cultures, supporting an important recruitment capacity of monocytes, but also of neutrophils." (PMID 28337194, 2017). "The chemokine CCL5 was secreted by MSCs, which in turn interacted with its receptor CCR5 on the breast cancer cells, resulting in increased metastasis to the lung." (PMID 28148268, 2017). "CCL5 and its receptor CCR5 represent significant therapeutic targets that should be considered in the future treatment of breast cancer." (PMID 29299159, 2017).
breast cancer (continued). "Previous research also suggested that CCL5/CCR3 signaling pathway is involved in prognosis and immunotherapy of luminal breast cancer." (PMID 27086913, 2016). "Here we show that suppression of either cancer cell produced CCL5, or host CCR5 leads to distinctive vascular and tumor growth defects in breast cancer." (PMID 27863423, 2016). "We demonstrate CCL5-inducible rapid activation of the mTOR/AKT pathway as well as phosphorylation of a downstream substrate, GSK3β, in breast cancer cells." (PMID 27335323, 2016). "Although CCL5 treatment increased ECAR, pre-treatment with rapamycin or maraviroc ablated this increase in all three breast cancer cell types." (PMID 27335323, 2016). "In the mammary tumors developed in mice, CXCL5 (a CXCR2 ligand) and CCL5 (a ligand for CCR1/3/5) can promote infiltration of MDSCs and Treg cells respectively, although their roles at metastatic sites remain to be identified." (PMID 26275794, 2015). "Coincidently CCR5 antagonists block metastasis formation of the breast cancer cell line MDA-MB-231 in mice, providing evidence for a key role of CCL5/CCR5 in the invasiveness of basal breast cancer cells." (PMID 26560478, 2015). "While knocking down of RKIP expression increased CCL5 expression, restoration of RKIP expression in low-RKIP-expressing breast cancer cells decreased CCL5 expression." (PMID 26375811, 2015). "Previous study indicated that CCL5 and SDF-1 secreted by MSCs was responsible for enhancing the metastatic potential of several breast cancer cells." (PMID 25654296, 2015). "Previously, we identified that key molecules (IL6, CSF2, CCL5, VEGFA, and VEGFC) secreted by tumor cells and stromal cells in basal breast cancer can promote metastasis." (PMID 26173622, 2015). "Hypoxia also promotes lymph node metastasis of breast cancer by increasing the expression of CCR5 on tumor cells and the ligand CCL5 in lymph nodes via the transcription factor hypoxia-inducible factor- (HIF-) 1α." (PMID 25110692, 2014). "In this study we chose two cytokines important in our breast cancer model and verified interaction with CXCL447–70 and CXCL4L147–70: EGF as growth factor for the tumor cells and CCL5 as attractant of monocytes/macrophages." (PMID 25373734, 2014). "MSCs produced CCL5 that stimulated growth and metastasis of MDA-MB-231 tumor xenografts, and ASCs produced CCL5 that stimulated migration and invasion of breast cancer cells in vitro." (PMID 24586900, 2014). "This recruitment enhances tumor growth through the secretion of an abundance of growth factors from ASCs, such as IL-6, CCL5 and PDGR, which have been shown to contribute to both the breast cancer tumorigenesis and the metastasis of breast cancer cells." (PMID 24176089, 2013). "Interaction of the chemokine CCL5 and its receptor CCR5 between MSCs and breast cancer cells, respectively, has been shown to enhance cancer cell motility, invasion and metastasis of breast cancer cells." (PMID 23936067, 2013). "On the other hand, ASCs can modulate the migration of cancer cells, promoting metastasis of breast cancer cells via CCR5/CCL5 signaling in animal models despite the inhibition of breast cancer metastasis in a different model." (PMID 24023546, 2013). "However, our analysis does not fit this prevailing hypothesis and suggests CCL5 is associated with good prognosis in high-grade breast cancer patients." (PMID 22789589, 2012). "Recently, much attention has been given to the roles of inflammatory chemokines and cytokines in breast cancer, with emphasis on the chemokines CCL2 and CCL5, and the cytokines tumor necrosis factor α (TNFα) and interleukin 1β (IL-1β)." (PMID 21486440, 2011). "In breast cancer, in vivo CCL5 neutralization or CCR5 antagonism were shown to abrogate the MSC-induced metastasis of cancer cells thus implicating CCL5/CCR5 as a key axis in this malignancy." (PMID 22205974, 2011).